TNF (tumor necrosis factor)
Diseases named in the same sentence as TNF in open-access papers (continued):
Sharing a sentence is not in itself a finding about the gene and the disease.
bacterial pneumonia (32 papers, 2006 to 2026). Acute infection of the lung parenchyma caused by bacteria (e.g., Streptococcus pneumoniae, Haemophilus influenzae, Chlamydia pneumoniae, Mycoplasma pneumoniae, and Legionella pneumophila). "In ARDS caused by bacterial pneumonia, components such as LPS can stimulate inflammatory cells (such as macrophages) by releasing cytokines for example TNF-α 42, which can activate Ripk3 via the death receptor pathway when bound to cell surface receptors." (PMID 39744171, 2025). "Previous studies have found that after infection with bacterial pneumonia, the concentrations of IL-2 and TNF-α in susceptible types were increased significantly and gradually decreased as inflammation declined." (PMID 37180342, 2023). "In patients with bacterial pneumonia, positive correlations were found between IL-6 and Veillonella parvula (p < 0.001), while TNF-α positively correlated with Capnocytophaga granulosa (p = 0.009)." (PMID 41011430, 2025). "It is well-established that inflammation activates coagulation and fibrinolysis in bacterial pneumonia, the latter primarily mediated by tumor necrosis factor alpha (TNF-α)." (PMID 35308535, 2022). "IL-1β and TNF levels were elevated in acute infection with concentrations exceeding those found in patients with bacterial pneumonia." (PMID 35732153, 2022). "The pro-inflammatory cytokine TNF-α is an important initiator of inflammatory and bactericidal processes, and in bacterial pneumonia, macrophage-derived TNF-α is elevated, leading to the recruitment of inflammatory cells to the site of infection." (PMID 35388320, 2022). "To study the influence of vendor effects on cytokine release in Gram-negative pneumonia, we measured the levels of TNFα and IL-6 in lung homogenates harvested from mice after intranasal infection with K. pneumoniae." (PMID 32840685, 2020). "In bacterial pneumonia, macrophage-derived TNF-α is elevated, resulting in recruitment of inflammatory cells to sites of infection." (PMID 30275916, 2018). "Because cytokines are important regulators of the inflammatory response to bacterial pneumonia, we measured pulmonary (TNF-α, IL-6, IL-10, CXCL1) and systemic (TNF-α, MCP-1, IL-6, IFN-γ, IL-10, IL12p70) cytokine and chemokine levels." (PMID 26215706, 2014). "The adhesion molecules are upregulated on alveolar epithelial cells in response to TNF-α stimulation or during bacterial pneumonias in vitro and in vivo." (PMID 24073006, 2013). "Some studies found that incubation with TNF was associated with a reduction in alveolar epithelial cell sodium transport in vitro while others found that in an in vivo model of bacterial pneumonia in rats TNF increased alveolar fluid clearance." (PMID 16571116, 2006). "Our study found that UC-MSCs can effectively inhibit the development of bacterial pneumonia, primarily by reducing the number of macrophages and neutrophils and inhibiting the secretion of inflammatory factors IL-1β, IL-6, and TNF-α, thereby suppressing in vivo inflammatory reactions." (PMID 40271073, 2025). "A retrospective cohort study from China explored differences in cytokine concentrations among patients with ARDS caused by AdV, influenza A/pH1N1, and bacterial pneumonia, and found higher expression of MCP-1, TNF-α, SDF-1α, IL-17, SCF-β, and TRAIL in the AdV group." (PMID 39858309, 2025). "We conclude that chronic exposure to TNF increases the expression of the glucocorticoid‐associated MAPK signaling suppressors, Dusp1 and Ptprs, which inhibits AM activation and increases susceptibility to bacterial pneumonia in older adults." (PMID 38459711, 2024). "Therefore, the upregulation of TNF-α by neutrophils might be TNFR independent in the bacterial pneumonia." (PMID 32685099, 2020). "IL-8, IL-10, IL-12, TNF-α, and IFN-γ were significantly increased in bacterial pneumonia and SARS-Cov-2 compared to healthy controls." (PMID 38585537, 2023).
bacterial pneumonia (continued). "Serum TNF-α levels are usually elevated in bacterial pneumonia and not significantly altered in viral pneumonia." (PMID 30275916, 2018). "This would be consistent with other prior observations that interleukin-6 and TNF are both profoundly induced by lysate treatment, but are not required for protection against bacterial pneumonias." (PMID 22299046, 2012). "IL-6 and TNF were even more robustly induced by the lysate than by Pam2-ODN, but we have shown that they were not required for protection against bacterial pneumonia." (PMID 22299046, 2012).
cystitis (32 papers, 2007 to 2025). Inflammation of the urinary bladder. "In this study we chose chemokines/cytokines IL-1β, IL-6, IL-8, and TNF-α because they are associated with cystitis and systemic inflammation." (PMID 24098552, 2013). "ALA can alleviate LPS-induced orchitis and cystitis in mice by inhibiting the activation of the NF-κB signaling pathway, thereby reducing the expression of the inflammatory factors IL-6, TNF-α, and COX-2." (PMID 40427376, 2025). "E. coli-induced up-regulation of TNF-α, IL-6, and IL-1β in cystitis rats were reversed by AAV-shTPRG1 injection, demonstrating that TPRG1 contributed to inflammation in E. coli-induced cystitis rat." (PMID 34998360, 2022). "Our previous study showed that the levels of several cytokines and chemokines increased in an autoimmune-induced model of cystitis and we have detected increases in systemic levels of TNF-α in other inflammatory models." (PMID 35720309, 2022). "We assessed the therapeutic effects of Tt-SOD on HCl-induced cystitis by detecting the serum levels of certain inflammatory factors (TNF-α, IL-1β and IL-6) by specific Elisa kits." (PMID 34783980, 2022). "We found that the expression of IL-1β and TNF-α were higher in the cystitis group than in the control group." (PMID 31931832, 2020). "Normalization of magnesium deficiency by L-TAMS attenuated mechanical allodynia, depressive-like behaviors, and STMD in the CYP-induced cystitis model via inhibition of TNF-α/NF-κВ signaling and normalization of NR2B expression." (PMID 32241292, 2020). "As expected we observed a strong proinflammatory response early in the infection with drastic upregulation of mRNA for inflammatory mediators such as IL-1, CXCL1 and TNF in the bladders of mice experiencing only cystitis or cystitis and pyelonephritis." (PMID 26907352, 2016). "In this study we used LPS to induce experimental cystitis model and we showed that SC significantly decreased urine TNF-α levels in treatment and preventive groups." (PMID 27355060, 2014). "This was confirmed by examination of the pro-inflammatory factors showing that interleukin (IL)-1α, IL-6 and tumor necrosis factor (TNF)α levels in the urinary bladder were increased with cystitis." (PMID 25486122, 2014). "In experimental studies, urine and bladder tissue TNF-α levels were found to be increased when the cystitis was induced with LPS." (PMID 27355060, 2014). "We showed that SC significantly reduced the TNF-α levels of urine when applied as preventive and treatment purpose in experimental cystitis model induced by LPS." (PMID 27355060, 2014). "Acute cystitis has been associated with an increase in urine IL-1α, GRO-α, IL-1β, IL-6, IL-8 and TNF-α compared to sterile samples." (PMID 22140570, 2011). "The described study shows that anti-CXCL10 Ab therapy reduces TNF-α expression that correlates with decreased cystitis severity." (PMID 18957084, 2008). "In PRV-induced cystitis, both genetic and pharmacologic data presented here suggest that mast cells mediate cystitis pain via H1R and H2R, whereas genetic data exclude TNF as a significant mediator of acute mast cell-dependent pelvic pain." (PMID 18461160, 2008). "The significant role of TNF-α in CYP-induced cystitis has been reported in the past and high levels of TNF-α have been observed in the urine of IC patients." (PMID 18957084, 2008). "As MB49-U-Exo administration induced macrophage apoptosis and suppressed their phagocytic activity, we next asked whether blocking exosome secretion or neutralizing TNFα activity could improve the severity of UPEC-induced cystitis." (PMID 38190378, 2024). "Moreover, a prior bladder infection can influence TNFα signaling dynamics, while sustained TNFα signaling activation is associated with tissue destruction and disease severity." (PMID 38190378, 2024). "We next asked whether exosomes isolated from the urine of mice with UPEC-induced cystitis could regulate TNFα expression in macrophages." (PMID 38190378, 2024).
cystitis (continued). "We showed that inhibiting exosome release using GW4869 or a TNFα-neutralizing antibody significantly ameliorated the pathology of UPEC-inducted cystitis in mice by promoting UPEC elimination by macrophages in the bladder but preventing excessive additional macrophage and neutrophil infiltration." (PMID 38190378, 2024). "Our results showed that the expression levels of TNF-α, IL-6, and IL-1β were enhanced in E. coli-induced cystitis rat, and knockdown of TPRG1 suppressed the inflammatory response in E. coli-induced cystitis rat through down-regulation of TNF-α, IL-6, and IL-1β." (PMID 34998360, 2022). "Furthermore, treatment with DAPT attenuated mechanical allodynia in CYP-induced cystitis and inhibited microglia activation, leading to decreased production of TNF-α and IL-1β." (PMID 34646085, 2021). "Inhibition of Notch1 signaling with a γ-secretase inhibitor, DAPT, could attenuate mechanical allodynia of cystitis animals by suppressing microglia activation as well as overexpression of TNF-α and IL-1β." (PMID 34646085, 2021). "Taken together, Notch1 signaling may promote microglia activation and production of TNF-α and IL-1β, contributing to mechanical allodynia associated with CYP-induced cystitis." (PMID 34646085, 2021). "We investigated this question in a mouse model of recurrent urinary tract infection and found that a prior bladder infection resulted in an earlier onset of tumor necrosis factor-alpha (TNFɑ)-mediated bladder inflammation upon subsequent bacterial challenge, relative to age-matched naive mice." (PMID 31429405, 2019). "However, the expression of IFN-γ, IL-12p40, and TNF-α mRNAs by urinary bladder lymphocytes from mice with cystitis were significantly decreased following anti-CXCL10 Ab treatment than compared to similar cells from CYP-induced mice treated with control Ab." (PMID 18957084, 2008). "Moreover, administration of the exosome secretion inhibitor GW4869 or a TNFα-neutralizing antibody alleviated UPEC-mediated tissue damage in mice with UPEC-induced cystitis by reducing the bacterial burden of the bladder and dampening the associated inflammatory response." (PMID 38190378, 2024). "Moreover, DAPT could inhibit microglia activation and reverse the upregulation of TNF-α and IL-1β in cystitis animals." (PMID 34646085, 2021). "Having shown that inhibiting TNFα production reduced the severity of UPEC-induced cystitis, we next investigated which factors within MB49-U-Exo induced TNFα production by macrophages." (PMID 38190378, 2024). "We also compared lectin binding to human urothelium with the two most cited experimental models of IC/BPS, specifically, TNFα-treated human urothelial cell line RT4 and cyclophosphamide-induced chronic cystitis in C57BL6/J mice." (PMID 35626233, 2022). "The establishment of the cystitis model in our present study needs three doses of CYP injections lasting one week, during which proinflammatory cytokines including TNF-α and IL-1β were gradually produced and accumulated." (PMID 34646085, 2021). "In our CYP-induced cystitis model, BDNF promoted the activation of astrocytes and microglia to release TNF-α and IL-1β, aggravating neuroinflammation and leading to mechanical allodynia through BDNF-TrkB-p38/JNK signaling." (PMID 31931832, 2020). "Neuroinflammation and synaptic plasticity play an important role in the mechanism of CYP-induced cystitis, and we found that TNF-α/NF-κB signaling and IL-1β were upregulated in both the SDH and hippocampus of the cystitis model." (PMID 32241292, 2020). "Our results provide evidence that BDNF promotes activation of astrocytes and microglia to release TNF-α and IL-1β contributing to aggravating the neuroinflammation and mechanical allodynia through BDNF-TrkB-p38/JNK signaling in CYP-induced cystitis." (PMID 31931832, 2020). "Effect of pregabalin (30 mg kg-1, s.c) on IL-6, KC and TNFα concentration in bladder and plasmatic level in cyclophosphamide (CYP)-induced cystitis mice model." (PMID 30863309, 2019).
cystitis (continued). "In contrast, although there is strong circumstantial evidence indicating that TNF-α plays a fundamental role in bladder inflammation, to our knowledge, the present study is the first to use intravesical TNF-α as a model for cystitis." (PMID 17506885, 2007). "Besides, the intrathecal injection of exogenous BDNF further decreased the mechanical withdrawal threshold, promoted activation of astrocytes and microglia, and increased the release of TNF-α and IL-1β in the SDH of our CYP-induced cystitis model." (PMID 31931832, 2020). "Cytokines and chemokines such as TNF-α, IL-6, and IL-8 have a crucial role in the bladder inflammation, and the increased levels of these cytokines have been reported in IC/BPS patients and the experimental cystitis model." (PMID 33133219, 2020). "Moreover, TNF-α/NF-κB signaling and pro-inflammatory IL-1β were both upregulated in the SDH and hippocampus of the cystitis rats." (PMID 32241292, 2020). "Furthermore, we explored the co-localization of TNF-α, p-p65 (a principal transcriptional regulator of the activation of the NF-kB pathway), and IL-1β in the SDH and hippocampus of cystitis model rats using double immunofluorescence staining." (PMID 32241292, 2020). "The results of the western blot analysis indicate that the upregulation of TNF-α, the p-p65/p65 ratio, and IL-1β in the SDH of the cystitis model following L-TAMS treatment was all significantly inhibited on day 20 when compared with the cystitis group without L-TAMS treatment." (PMID 32241292, 2020). "Surprisingly, oral application of L-TAMS could reverse and normalize the expression changes in TNF-α/NF-κB signaling, IL-1β, and NR2B in both the SDH and hippocampus of the CYP-induced cystitis model." (PMID 32241292, 2020). "TNF-α is a potent inducer of CXCL10 expression by endothelial cells; this inflammatory cytokine was negatively modulated by CXCL10 blockade during CYP-induced cystitis." (PMID 18957084, 2008). "Indeed, the numbers of macrophages and neutrophils were significantly lower in the bladders of model mice with UPEC-induced cystitis that were treated with GW4869 or the TNFα-neutralizing antibody than in those that were not." (PMID 38190378, 2024). "Therefore, we performed a western blot analysis and immunofluorescence staining to determine TNF-α/NF-κB signaling as well as IL-1β expression in the SDH and hippocampus of CYP-induced cystitis rats and compared the expression level between groups with and without L-TAMS treatment." (PMID 32241292, 2020). "TNF mediated cystitis pathophysiology, while pelvic pain developed independent of TNF." (PMID 18461160, 2008). "However, the role of TNF-α/NF-κB signaling and IL-1β expression in the SDH and hippocampus of the CYP-induced cystitis model has not yet been clearly identified." (PMID 32241292, 2020).
esophageal cancer (32 papers, 2012 to 2025). A primary or metastatic malignant neoplasm involving the esophagus. "On the other hand, cisplatin caused RIP3-dependent necroptosis in apoptosis-resistant esophageal cancer cells through necrosome formation that was triggered by autocrine TNF-α signaling." (PMID 30583560, 2018). "Many studies have investigated the association between Tumor necrosis factor-α-308 G>A (rs1800629) and the risk of esophageal cancer." (PMID 27821804, 2016). "Additionally, including IL-1β and IL-6 and TNF-α have been linked also with the pathogenesis of esophageal cancer." (PMID 34830880, 2021). "The plasma expression levels of IL-32 in patients with malignant esophageal cancer increased, promoting the progression of esophageal cancer through the activation of NF-κB and the increased levels of cytokines TNF-α, IL-6, and IL-1β40." (PMID 38584169, 2024). "Here, we found that lactate can also enhance the promigratory effect of TNF-α in esophageal cancer cells by intensifying TNF-α-related MMP9 expression, and the use of SO stopped this activity." (PMID 36555705, 2022). "Our previous studies have shown that TNF-α regulates the migration of cancer cells, including esophageal cancer, by affecting the expression of MMP9." (PMID 36555705, 2022). "In contrast, SO significantly reduced lactate production in esophageal cancer cells, even when the cells were additionally stimulated with TNF-α." (PMID 36555705, 2022). "We also reveal that in esophageal cancer cells, SO effectively reduces the production of lactic acid, which, as we have shown, synergizes the stimulating effect of TNF-α on MMP9 expression." (PMID 36555705, 2022). "A close relationship between the metabolic status of esophageal cancer cells and the pro-tumor effects of TNF-α was confirmed when cells were treated with SO." (PMID 36555705, 2022). "The expression of proinflammatory M1 macrophage genes such as IL1β and TNFα were significantly downregulated in esophageal carcinoma tissues, while M2 marker genes TGFβ1 and MRC1 were upregulated." (PMID 34612767, 2021). "The data from The Cancer Genome Atlas (TCGA) were used to analyze the differential expression of TNF-α and Tim-3 in tumor tissues and adjacent tissues from esophageal cancer patients." (PMID 31109341, 2019). "In both animal models and patients, the Tim-3 level was positively correlated with TNF-α expression in esophageal cancer tissues." (PMID 31109341, 2019). "The crosstalk between TNF-α and the Hh pathway has been reinforced by the finding that blockage of the mTOR pathway enhances the suppressive effect of the Hh inhibitor in esophageal carcinoma." (PMID 29695137, 2018). "Our data indicate that RIPK3, necrosomes and autocrine production of TNFα contribute to cisplatin sensitivity by initiating necrosis when the apoptotic pathway is blocked in esophageal cancer cells." (PMID 24959694, 2014). "The TNF-α-mediated upregulation of SOD2 is involved in cisplatin resistance in esophageal cancer." (PMID 36672191, 2023). "In esophageal cancer, TNFα suppresses NK cell function via NF-κB." (PMID 36996146, 2023). "To assess whether TNF-α is involved in the regulation of LDH in esophageal cancer cells, we analyzed the expression levels of genes encoding LDH subunits (LDHA and LDHB) in TNF-α-treated KYSE150 and EC7 cells versus untreated cells using qPCR." (PMID 36555705, 2022). "Therefore, the aim of the present study was to investigate the interrelationship between the TNF-α-induced promigratory activity of cancer cells and their glucose metabolism status, using esophageal cancer cells as an example." (PMID 36555705, 2022). "The current study showed that TNF-α could also moderately modulate glucose metabolism by increasing the expression of LDH subunits in esophageal cancer cells." (PMID 36555705, 2022). "Additionally, these TNFα signaling signature genes were also ectopically overexpressed in TCGA esophageal cancer tissues." (PMID 36274060, 2022).